Y_RNA (Y RNA )
Gene: Miscellaneous RNA gene on chromosome 4 (39,441,665 to 39,441,764, forward strand). Ensembl gene ENSG00000238797.
Homologues: Orthologues: chimpanzee Y_RNA (95% identical), macaque Y_RNA (92% identical). Paralogues in human: Y_RNA (86% identical), Y_RNA (85% identical), Y_RNA (84% identical), RNY3 (83% identical), Y_RNA (83% identical), RNY3P1 (82% identical), Y_RNA (82% identical), RNY3P14 (81% identical), RNY3P7 (81% identical), Y_RNA (81% identical), RNY3P11 (80% identical), Y_RNA (80% identical), and 94 more.